RBM44 (RNA binding motif protein 44)
Description:
Component of intercellular bridges during meiosis. Intercellular bridges are evolutionarily conserved structures that connect differentiating germ cells. Not required for fertility (By similarity).
Synonyms: FLJ40411
Tractability: No criterion of Open Targets' tractability assessment is met for any kind of drug.
Gene: Protein-coding gene on chromosome 2 (237,798,389 to 237,842,808, forward strand). Ensembl gene ENSG00000177483.
Subcellular location: Cytoplasm
Subcellular location (Human Protein Atlas): Cytosol
Gene Ontology:
Molecular function: mRNA 3'-UTR binding; protein homodimerization activity; nucleic acid binding; RNA binding
Biological process: mRNA splicing, via spliceosome
Cellular component: catalytic step 2 spliceosome; cytoplasm; intercellular bridge
Genetic constraint (gnomAD): Loss-of-function variants: 43 observed, 61.54 expected, observed/expected ratio (o/e) 0.7, 90% interval 0.55 to 0.9. The upper end of that interval is the gene's LOEUF score, 0.9, which puts it in group 3 of 6, group 1 being the genes least tolerant of losing a copy. Missense variants: 758 observed, 846.97 expected, observed/expected ratio (o/e) 0.89, 90% interval 0.84 to 0.95. Synonymous variants: 261 observed, 306.12 expected, observed/expected ratio (o/e) 0.85, 90% interval 0.77 to 0.94.
Homologues: Orthologues: chimpanzee RBM44 (97% identical), macaque RBM44 (93% identical), dog RBM44 (72% identical), pig RBM44 (66% identical), guinea pig RBM44 (62% identical), rabbit RBM44 (60% identical), mouse Rbm44 (55% identical), rat Rbm44 (54% identical).